XPO5 (exportin 5)
Diseases named in the same sentence as XPO5 in open-access papers (continued):
Sharing a sentence is not in itself a finding about the gene and the disease.
COVID-19 (3 papers, 2023 to 2024). A disease caused by infection with severe acute respiratory syndrome coronavirus 2. "mRNA levels of AGO2, DICER1, DGCR8, DROSHA, and Exportin-5 (XPO5) were measured by quantitative reverse-transcription polymerase chain reaction (RT-qPCR) in nasopharyngeal swab specimens from patients with COVID-19 and controls, as well as in cells infected with SARS-CoV-2 in vitro." (PMID 37243263, 2023). "Therefore, prospective studies are needed to collect human lung tissue samples before SARS-CoV-2 infection and determine whether pre-infection levels of Dicer, XPO5, SRSF3, and hnRNPA3 are associated with COVID-19 severity." (PMID 39138195, 2024). "Herein, we show that decreased RNAi component (Dicer and XPO5) and splicing factor (SRSF3 and hnRNPA3) expression correlate with increased COVID-19 severity." (PMID 39138195, 2024). "Measured mRNA levels of AGO2, DICER1, DGCR8, DROSHA, and XPO5 were not significantly different in nasopharyngeal swab specimens of severe COVID-19 patients compared to non-severe COVID-19 patients or controls." (PMID 37243263, 2023). "Our data showed that the mRNA expression levels of AGO2, DICER1, DGCR8, DROSHA, and XPO5 were not significantly different in patients with severe COVID-19 when compared to patients with non-severe COVID-19 and controls." (PMID 37243263, 2023).
Wilms tumor (3 papers, 2021 to 2022). An embryonal neoplasm characterized by the presence of epithelial, mesenchymal, and blastema components. "Among the miRNA-processing genes, mutations in DROSHA, DGCR8, DICER1, TARBP2, and XPO5 (encodes exportin 5) have been reported in treatment-naive and neoadjuvant chemotherapy-treated Wilms tumors." (PMID 35531954, 2022). "With exception of hotspot mutations found in DICER1, we found only a few mutations in other miRNA biogenesis genes, i.e. DROSHA, DGCR8 and XPO5, which have been recently observed in different childhood cancers associated with DICER1 syndrome and in Wilms' tumor." (PMID 33406242, 2021).
bladder cancer (2 papers, 2017 to 2019). "We speculate that the over-expression of XPO5 might accelerate the transportation of tumour-promoting miRNAs to the cytoplasm and therefore alter the expression profile of miRNAs in bladder cancer." (PMID 28187437, 2017). "Silencing XPO5 inhibits proliferation and promotes the apoptosis of bladder cancer cells." (PMID 28187437, 2017).
breast tumors (2 papers, 2018 to 2021). "XPO5‐inactivating mutations are detected in endometrial, colon, gastric, and breast tumors with microsatellite instability, causing impaired pre-miRNA export and are associated with increased cancer risk." (PMID 34853298, 2021).
endometrial cancer (2 papers, 2016 to 2019). Primary or metastatic malignant neoplasm involving the endometrium (mucous membrane that lines the endometrial cavity). "Pre-miRNAs are exported into the cytoplasm to generate mature miRNAs through XOP5 and it cofactor RAN, some heterozygous XPO5 variations were found in colon, gastric and endometrial cancer." (PMID 27957388, 2016).
endometrial tumors (2 papers, 2017 to 2021). "Of the indel hotspots in XPO5 and TARBP2 detected previously in colon, gastric, and endometrial tumors with MSI, we detected only two cases of the C insertion in the poly-C track (p.M145HfsTer13) in TARBP2: one in UCEC and one in STAD (both cancers often characterized by MSI)." (PMID 33406242, 2021).
Hearing Loss (2 papers, 2020). "Reducing the expression of XPO5 can decrease the expression of miRNAs, which may lead to the occurrence and development of hearing loss." (PMID 32148964, 2020).
larynx cancer (2 papers, 2015 to 2018). A primary or metastatic malignant neoplasm involving the larynx. "This is the first report considering the association of the risk of larynx cancer and SNPs of the following polymorphisms: DROSHA (rs6877842), DGCR8 (rs3757, rs417309, and rs1640299), RAN (rs14035), XPO5 (rs11077), DICER1 (rs13078 and rs3742330), and TARBP2 (rs784567)." (PMID 26688807, 2015).
leukoplakia (2 papers, 2014 to 2025). A white patch or plaque on a mucous membrane that cannot be characterized clinically or pathologically as any other disease. "In order to compare expression of Gemin3, Xpo5, mir34b, mir29a, mir423 on the basis of genotypes, we calculated ΔCt value in leukoplakia tissues with respect to endogenous gene (Ctgene of interest – Ct RNASEP or RNU44)." (PMID 24885463, 2014).
liver cancer (2 papers, 2018 to 2024). An epithelial or non-epithelial malignant neoplasm that arises from the liver. "Decreased levels of XPO5 protein expression has been linked with a worst prognosis of renal and esophageal tumors, whereas a better prognosis has been seen in multiple myeloma, liver cancer and in non-small-cell lung cancer." (PMID 30018188, 2018). "Recently, the role of XPO5 has been investigated in liver cancer." (PMID 30018188, 2018). "Our previous research found that exportin‐5 (XPO5) is also a substrate of PP2A, which inhibits XPO5 phosphorylation at Ser416, thereby regulating XPO5's pre‐miRNA transport capacity and promoting miRNA expression to modulate liver cancer progression." (PMID 39399646, 2024).
melanoma (2 papers, 2016 to 2020). A malignant, usually aggressive tumor composed of atypical, neoplastic melanocytes. "The enhanced XPO5 expression is partly due to constitutively active MEK/ERK signaling in melanoma and partly due to increased mRNA stability because of a single nucleotide polymorphism (SNP; rs11077) in the miR-617 binding site." (PMID 31906510, 2020). "We suggest that the high abundance of XPO5 in melanoma leads to enhanced survival, proliferation and metastasis and thereby supports the aggressiveness of melanoma." (PMID 27556702, 2016). "We showed enhanced XPO5 mRNA stability in melanoma cell lines which likely contributes to up-regulated XPO5 protein expression." (PMID 27556702, 2016). "Knockdown of XPO5 expression in melanoma cells led to decreased mature miRNA levels and drastic functional changes." (PMID 27556702, 2016). "Our data revealed that aberrant XPO5 expression is important for the maturation of miRNAs and the malignant behavior of melanoma cells." (PMID 27556702, 2016). "We found that XPO5 is significantly over-expressed in melanoma compared with melanocytes." (PMID 27556702, 2016). "Therefore, we investigated whether the pre-miRNA transporter Exportin-5 (XPO5) was involved in altered miRNA maturation and functional consequences in melanoma." (PMID 27556702, 2016). "In addition, we identified MEK signaling as a regulator of XPO5 expression in melanoma." (PMID 27556702, 2016). "We identified XPO5 as significantly overexpressed in melanoma compared to normal human epidermal melanocytes (NHEM), contributing to enhanced survival, proliferation and metastasis of melanoma cells." (PMID 31906510, 2020).
adenomyosis (1 paper, 2022). The growth of endometrial tissue inside the muscular wall of the uterine corpus. "The objective of this study was to evaluate the immunohistochemical expression of Dicer, Drosha, and Exportin-5 in the eutopic and ectopic endometrium of women with adenomyosis." (PMID 36515351, 2022). "This pilot study aims to evaluate the immunohistochemical expression of the Dicer, Drosha, and Exportin-5 proteins in the eutopic and ectopic endometrium of women with adenomyosis." (PMID 36515351, 2022). "We did not observe any difference in Exportin-5 expression between the eutopic endometrium of women with adenomyosis and the eutopic endometrium of women without the disease (76.3±2.6% vs 67.8±7.6%) (P=0.428; 95%CI of the difference: -18.1 to 7.9%)." (PMID 36515351, 2022).
adult T cell Leukemia (1 paper, 2023). "Interestingly, the authors measured DROSHA, DGCR8, XPO5, DICER1, AGO2, and AGO3 mRNA expression, and only DICER1 mRNA was differently expressed in CD8+ T-cell–depleted PBMCs from HTLV-1 asymptomatic carriers when compared to patients with acute adult T cell Leukemia." (PMID 37243263, 2023).
Alzheimer disease (1 paper, 2021). A progressive, neurodegenerative disease characterized by loss of function and death of nerve cells in several areas of the brain leading to loss of cognitive function such as memory and language. "Expression of KPNB1 and XPO5/exportin-5 were both found to be upregulated in Alzheimer’s disease cases and both proteins co-localized with hyperphosphorylated tau." (PMID 34019093, 2021).
bladder tumors (1 paper, 2019).
depression (1 paper, 2024). "We believe that SNPs in DROSHA (rs10719 and rs6877842) and XPO5 (rs11077) are associated with an increased risk of depression." (PMID 39596271, 2024). "In our study, we identified a connection between rs11077 in XPO5 and an increased risk of depression." (PMID 39596271, 2024). "It turns out that polymorphism of the rs11077/XPO5 gene also induces depression, but it is still unknown how this is done." (PMID 39596271, 2024). "Given that XPO5 is crucial for the nuclear export of pre-miRNAs, including miR-16, polymorphisms such as rs11077 could disrupt this export process, potentially leading to altered serotonin signaling and contributing to the pathogenesis of depression." (PMID 39596271, 2024). "In our research, we sought to determine whether specific single-nucleotide polymorphisms (SNPs) in genes associated with nuclear microRNA processing, namely, DROSHA (rs6877842; rs10719) and XPO5 (rs11077), are linked with depression risk in the Polish population." (PMID 39596271, 2024). "A correlation with depression was observed in the rs10719/DROSHA, rs6877842/DROSHA, and rs11077/XPO5 polymorphisms." (PMID 39596271, 2024). "Findings indicated that within our patient cohort, the risk of depression is increased by polymorphic variants of the rs10719/DROSHA and rs11077/XPO5 genes and lowered by rs6877842/DROSHA." (PMID 39596271, 2024). "The aim of our research was to assess the relationship between the occurrence of depression and single-nucleotide polymorphisms (SNP) in the following genes in the Polish population: DROSHA (rs6877842; rs10719) and XPO5 (rs11077)." (PMID 39596271, 2024). "The T/G genotype of the rs11077/XPO5 polymorphism and the A/G genotype of the rs10719/DROSHA polymorphism increased the risk of depression, whereas the G/C and C/C genotypes of the rs6877842/DROSHA polymorphism lowered the risk of depression." (PMID 39596271, 2024). "Such an approach may provide valuable insights into whether these specific SNPs in DROSHA and XPO5 contribute to recurrent episodes of depression, thereby offering insights into the genetic factors that influence the likelihood of relapse." (PMID 39596271, 2024).
endometriosis (1 paper, 2023). The growth of functional endometrial tissue in anatomic sites outside the uterine body. "Our goal, therefore, was to evaluate whether the gene expressions of DROSHA, DGCR8, XPO5, DICER, and AGO1 to AGO4 are differential in MenSCs of women with endometriosis." (PMID 36983035, 2023).
glaucoma (1 paper, 2023). Increased pressure in the eyeball due to obstruction of the outflow of aqueous humor. "But we cannot completely rule out the role of different polymorphisms in these or other genes (e.g., DGCR8, XPO5) significant to the miRNA biogenesis pathway in glaucoma." (PMID 37099569, 2023).
glomerulosclerosis (1 paper, 2022). A hardening of the kidney glomerulus caused by scarring of the blood vessels. "Thirdly, mutant XPO5 can cause podocyte dysfunction because our patients showed higher levels of proteinuria and glomerulosclerosis." (PMID 36371311, 2022). "Hence, any abnormality in XPO5 can cause podocyte injury, which is the major cause of proteinuria and glomerulosclerosis as described by Michio N." (PMID 36371311, 2022).
hereditary nonpolyposis colon cancer (1 paper, 2018). "Inactivating mutations in XPO5 gene have been detected in a subset of human tumors with microsatellite instability, such as hereditary nonpolyposis colon cancer (HNPCC)." (PMID 29723684, 2018).
Hodgkins lymphoma (1 paper, 2015). A heterogeneous group of malignant lymphoid neoplasms of B-cell origin characterized histologically by the presence of Hodgkin and Reed-Sternberg (HRS) cells in the vast majority of cases. "Patients with Hodgkin Lymphoma that were carriers of both XPO5 AA/CC and TARBP2 TT/TC genotypes had the shortest disease free survival (p = 0.008) and overall survival (p = 0.008)." (PMID 26688807, 2015).
Hypertension (1 paper, 2015). The presence of chronic increased pressure in the systemic arterial system. "Furthermore, patients diagnosed with hypertension or DM who carried the DROSHA rs10719 CC genotype showed increased CRC risk, while the XPO5 rs11077 AC+CC genotype led to increased CRC risk in patients with hypertension only." (PMID 26147304, 2015).
laryngeal carcinoma (1 paper, 2015). Carcinoma that arises from the laryngeal epithelium. "Our results suggest that rs3742330 of DICER1, rs13078 of DICER1, and rs784567 of TARBP2 as well as rs11077 of XPO5 might be associated with a risk of laryngeal cancer occurrence in the Polish population." (PMID 26688807, 2015).
medullary thyroid carcinomas (1 paper, 2019). "Moreover, XPO5 was overexpressed in medullary thyroid carcinomas harboring RET mutations." (PMID 31371628, 2019). "On one hand, the significant overexpression of XPO5 was found in breast, prostate and medullary thyroid carcinomas." (PMID 31371628, 2019).
mesothelioma (1 paper, 2022). A usually malignant and aggressive neoplasm of the mesothelium which is often associated with exposure to asbestos. "AUNIP, FANCI, LASP1, PSMD8, and XPO5 are putative antigens for the development of anti-mesothelioma mRNA vaccine and patients with the IS1 subtype may be considered for vaccination." (PMID 35846349, 2022). "A Kaplan-Meier survival analysis revealed that high expressions of AUNIP, FANCI, LASP1, PSMD8, and XPO5 were clearly associated with poor OS and RFS, suggesting that the five candidate genes play important roles in the tumorigenesis and progression of mesothelioma." (PMID 35846349, 2022).
metastatic disease (1 paper, 2019). "In addition, over-expression of EIF2C2-4 was associated with the presence of distant metastases, while the up-regulation of XPO5 correlated with the clinical stage and metastatic disease." (PMID 31510013, 2019).
nephropathies (1 paper, 2022). "Additionally, the identification of the new inheritance pattern and the difference in onset age for XPO5 can help us understand the recurrence risk within the families and the genetic counseling of such complicated impending nephropathies." (PMID 36371311, 2022).
neuroblastoma (1 paper, 2023). Neuroblastoma (NB) is the most common solid, extracranial childhood tumor. "Endogenous PrP (bait) was immunoprecipitated from a human neuroblastoma cell line (SH-SY5Y) and XPO5 (prey) was probed by western blotting." (PMID 38041189, 2023).
pneumonia (1 paper, 2024). An acute, acute and chronic, or chronic inflammation focally or diffusely affecting the lung parenchyma, caused by an infection in one or both of the lungs (by bacteria, viruses, fungi, or mycoplasma.). "Treatment with PJ34 or anastrozole alleviates the N protein-induced DNA damage, proteotoxic stress, and pneumonia by rescuing Dicer, XPO5, SRSF3, and hnRNPA3 expression." (PMID 39138195, 2024). "In summary, N protein leads to autophagic degradation of Dicer, XPO5, SRSF3, and hnRNPA3, inducing DNA damage and proteotoxic stress and eventually causing pneumonia." (PMID 39138195, 2024). "Age-associated downregulation of Dicer, XPO5, SRSF3, and hnRNPA3 expression in lung tissues increases the severity of N protein-induced pneumonia." (PMID 39138195, 2024). "Collectively, these results reveal that anastrozole alleviates SARS-CoV-2 N protein-induced pneumonia by promoting Dicer, XPO5, SRSF3, and hnRNPA3 expression." (PMID 39138195, 2024). "Collectively, these results indicate that PJ34 alleviates pneumonia by preventing the N protein-induced downregulation of Dicer, XPO5, SRSF3, and hnRNPA3." (PMID 39138195, 2024). "Here, the authors provide evidence that SARS-CoV-2 N protein leads to autophagic degradation of Dicer, XPO5, SRSF3, and hnRNPA3, inducing DNA damage and proteotoxic stress, eventually causing pneumonia." (PMID 39138195, 2024). "PJ34, a poly(ADP-ribose) polymerase inhibitor, or anastrozole, an aromatase inhibitor, ameliorates N protein- or SARS-CoV-2-induced pneumonia by restoring Dicer, XPO5, SRSF3, and hnRNPA3 expression." (PMID 39138195, 2024). "The age-associated downregulation of Dicer, XPO5, SRSF3, and hnRNPA3 expression in lung tissues is one of the reasons why older individuals are more prone to developing severe pneumonia after SARS-CoV-2 infection than younger ones." (PMID 39138195, 2024). "Here, we found that anastrozole alleviated N protein- or SARS-CoV-2-induced pneumonia by promoting Dicer, XPO5, SRSF3, and hnRNPA3 expression." (PMID 39138195, 2024). "Therefore, age-associated downregulation of Dicer, XPO5, SRSF3, and hnRNPA3 expression in lung tissues may render older individuals more prone to developing severe pneumonia after SARS-CoV-2 infection." (PMID 39138195, 2024). "Treatment with PJ34 increased the expression of Dicer, XPO5, SRSF3, and hnRNPA3 in SARS-CoV-2-infected lung tissues and ameliorated the pneumonia induced by ectopic N protein expression and SARS-CoV-2 infection." (PMID 39138195, 2024). "Dicer, XPO5, SRSF3, and hnRNPA3 knockdown in lung tissues led to lung injury and pneumonia, whereas their overexpression partially alleviated N protein-induced pneumonia." (PMID 39138195, 2024). "Older mice show lower expression of Dicer, XPO5, SRSF3, and hnRNPA3 in their lung tissues and exhibit more severe N protein-induced pneumonia than younger mice." (PMID 39138195, 2024). "The effects of anastrozole on the expression of Dicer, XPO5, SRSF3, and hnRNPA3 and pneumonia were also observed in the SARS-CoV-2-infected mouse model." (PMID 39138195, 2024). "Dicer, XPO5, SRSF3, and hnRNPA3 knockdown increases, while their overexpression decreases, N protein-induced pneumonia’s severity." (PMID 39138195, 2024). "SARS-CoV-2 N protein induces the autophagic degradation of Dicer, XPO5, SRSF3, and hnRNPA3, inhibiting miRNA biogenesis and RNA splicing and triggering DNA damage, proteotoxic stress, and pneumonia." (PMID 39138195, 2024). "Moreover, we found that anastrozole promotes Dicer, XPO5, SRSF3, and hnRNPA3 expression and ameliorates N protein-induced pneumonia not only in young mice but also in old mice." (PMID 39138195, 2024). "Dicer, XPO5, SRSF3, and hnRNPA3 knockdown increased the severity of N protein-induced pneumonia." (PMID 39138195, 2024). "Dicer, XPO5, SRSF3, and hnRNPA3 expression was downregulated in the lung tissues of older mice compared with that in younger mice, and N protein induced more severe lung injury and pneumonia in older mice." (PMID 39138195, 2024).